LRRC69 (leucine rich repeat containing 69)
Tractability: Antibody: the Human Protein Atlas places it where antibodies can reach. PROTAC: ubiquitination databases record sites on it.
Gene: Protein-coding gene on chromosome 8 (91,101,832 to 91,219,257, forward strand). Ensembl gene ENSG00000214954.
Subcellular location (Human Protein Atlas): Plasma membrane
Gene Ontology:
Biological process: intracellular signal transduction
Genetic constraint (gnomAD): Loss-of-function variants: 23 observed, 21.69 expected, observed/expected ratio (o/e) 1.06, 90% interval 0.76 to 1.5. The upper end of that interval is the gene's LOEUF score, 1.5, which puts it in group 6 of 6, group 1 being the genes least tolerant of losing a copy. Missense variants: 206 observed, 229.1 expected, observed/expected ratio (o/e) 0.9, 90% interval 0.8 to 1.01. Synonymous variants: 83 observed, 82.18 expected, observed/expected ratio (o/e) 1.01, 90% interval 0.85 to 1.21.
Homologues: Orthologues: chimpanzee LRRC69 (99% identical), pig LRRC69 (79% identical), guinea pig LRRC69 (79% identical), rabbit LRRC69 (78% identical), dog LRRC69 (77% identical), mouse Lrrc69 (67% identical), rat Lrrc69 (66% identical), Caenorhabditis elegans let-413 (25% identical). Paralogues in human: ERBIN (27% identical), LRRC7 (25% identical), SCRIB (24% identical), LRCH3 (24% identical), LRRD1 (23% identical), LRCH1 (23% identical), SHOC2 (23% identical), LRCH2 (23% identical), LRRC40 (23% identical), PHLPP1 (23% identical), PHLPP2 (22% identical), PIDD1 (22% identical), and 19 more.
Diseases named in the same sentence as LRRC69 in open-access papers:
LRRC69 is named in the same sentence as 2 diseases in open-access papers, as found by Europe PMC text mining. Sharing a sentence is not in itself a finding about the gene and the disease. The quoted sentences say what the papers report.
male infertility (1 paper, 2023). The inability of the male to effect fertilization of an ovum after a specified period of unprotected intercourse. "As a secondary outcome, a recurrent deletion within the testis-specific LRRC69 gene was identified as a novel candidate risk factor for male infertility." (PMID 36631630, 2023).
LRRC69 also shares sentences with these, for which no sentence is quoted: breast invasive carcinoma (1 paper).